GUCY2D (guanylate cyclase 2D, retinal)
Description:
Catalyzes the synthesis of cyclic GMP (cGMP) in rods and cones of photoreceptors. Plays an essential role in phototransduction, by mediating cGMP replenishment. May also participate in the trafficking of membrane-associated proteins to the photoreceptor outer segment membrane (By similarity).
Synonyms: RETGC-1; ROS-GC; CORD6; GUC1A4; GUC2D; RETGC; ROS-GC1; CYGD; LCA1; CACD; CACD1; CG-E; CORD5; CSNB1I; LCA; RCD2; ROSGC
Tractability: Small molecule: it belongs to a druggable protein family. Antibody: its Gene Ontology location is reachable by antibodies, with high confidence; UniProt predicts a signal peptide or a membrane-spanning region.
Gene: Protein-coding gene on chromosome 17 (8,002,615 to 8,020,342, forward strand). Ensembl gene ENSG00000132518.
Subcellular location: Photoreceptor outer segment membrane; Endoplasmic reticulum membrane
Pathways (Reactome):
Sensory Perception: Inactivation, recovery and regulation of the phototransduction cascade
Gene Ontology:
Molecular function: guanylate cyclase activity; protein binding; peptide receptor activity; protein homodimerization activity; signaling receptor activity; ATP binding; identical protein binding; phosphorus-oxygen lyase activity; protein heterodimerization activity; protein kinase activity
Biological process: regulation of opsin-mediated signaling pathway; cGMP biosynthetic process; receptor guanylyl cyclase signaling pathway; visual perception; cGMP metabolic process; cyclic nucleotide biosynthetic process; intracellular signal transduction
Cellular component: endoplasmic reticulum membrane; photoreceptor outer segment; photoreceptor outer segment membrane; nuclear outer membrane; photoreceptor disc membrane; plasma membrane; rod photoreceptor disc membrane
Genetic constraint (gnomAD): Loss-of-function variants: 65 observed, 87.7 expected, observed/expected ratio (o/e) 0.74, 90% interval 0.61 to 0.91. The upper end of that interval is the gene's LOEUF score, 0.91, which puts it in group 3 of 6, group 1 being the genes least tolerant of losing a copy. Missense variants: 1,444 observed, 1,446.2 expected, observed/expected ratio (o/e) 1, 90% interval 0.95 to 1.04. Synonymous variants: 681 observed, 624.44 expected, observed/expected ratio (o/e) 1.09, 90% interval 1.02 to 1.16.
Gene-disease validity (ClinGen):
ClinGen rates the evidence that GUCY2D causes each of these diseases.
GUCY2D-related dominant retinopathy (autosomal dominant): Definitive. A retinopathy caused by a heterozygous gain of function or dominant-negative variant or in the GUCY2D gene.
GUCY2D-related recessive retinopathy (autosomal recessive): Definitive. A retinopathy caused by biallelic variants in the GUCY2D gene.
Homologues: Orthologues: chimpanzee GUCY2D (99% identical), macaque GUCY2D (92% identical), pig GUCY2D (88% identical), dog GUCY2D (87% identical), mouse Gucy2e (85% identical), rat Gucy2e (85% identical), rabbit GUCY2D (83% identical), guinea pig GUCY2D (83% identical), tropical clawed frog gucy2d (29% identical), tropical clawed frog gucy2d (6% identical). Paralogues in human: GUCY2F (50% identical), NPR2 (31% identical), NPR1 (31% identical), GUCY2C (28% identical), ADCY6 (17% identical), ADCY3 (16% identical), GUCY1A2 (16% identical), ADCY5 (16% identical), ADCY7 (16% identical), ADCY8 (16% identical), ADCY1 (16% identical), ADCY2 (15% identical), and 5 more.
Diseases named in the same sentence as GUCY2D in open-access papers:
GUCY2D is named in the same sentence as 24 diseases in open-access papers, as found by Europe PMC text mining. Sharing a sentence is not in itself a finding about the gene and the disease. The quoted sentences say what the papers report.
Leber congenital amaurosis (10 papers, 2010 to 2025). Leber congenital amaurosis (LCA) is a retinal dystrophy defined by blindness and responses to electrophysiological stimulation (Ganzfeld electroretinogram (ERG)) below threshold, associated with severe visual impairment within the first year of life. "Loss-of-function mutations in human GUCY2D cause LCA1, one of the most common forms of Leber congenital amaurosis, which results in blindness at birth or in early childhood." (PMID 36698779, 2022). "Mutations in GUCY2D, the gene that encodes retGC1, are a leading cause of the most severe form of early onset retinal dystrophy, Leber congenital amaurosis (LCA1)." (PMID 24860425, 2014). "Recessive mutations in guanylate cyclase-1 (Gucy2d) are associated with severe, early onset Leber congenital amaurosis-1(LCA1)." (PMID 20593011, 2010). "Testing was performed with a three-alternative forced choice method in healthy subjects and patients with Leber congenital amaurosis (LCA) caused by mutations in GUCY2D, the gene that encodes retinal guanylate cyclase-1." (PMID 26253563, 2015). "Based on previous animal studies and the clinical cases describing loss of function in RetGC1 associated with a recessive blindness, GUCY2D Leber’s congenital amaurosis, RetGC1 is the main isozyme of RetGC providing most of cGMP production in mammalian photoreceptors, including human rods and cones." (PMID 39909376, 2025).
Cone rod dystrophy (9 papers, 2008 to 2025). "Until now, four LCA genes account for congenital cone-rod dystrophy (LCA type I): GUCY2D, RPGRIP1, CEP290 and RD3 [present study]." (PMID 23308101, 2013). "There is a transgenic cone-rod dystrophy model with mutant human GUCY2D, which produces the protein retinal guanylate cyclase-1 (RETGC1)." (PMID 33435268, 2021). "The genes involved in cone degeneration, CNGB3, CNGA3 and GNAT2, and the genes involved in cone-rod dystrophy, ABCA4, RDH5, Cord8, Cord9, RPGRIP1, GUCY2D and CRX, were all excluded from being involved in the cone-rod dystrophy described in this family of SWHD." (PMID 18593457, 2008). "Three of the genes, CNGB3, CNGA3 and GNAT2, involved in cone degeneration and seven genes and loci, ABCA4, RDH5, CORD8, CORD9, RPGRIP1, GUCY2D and CRX, reported to be involved in cone-rod dystrophies were studied." (PMID 18593457, 2008).
retinal dystrophies (8 papers, 2013 to 2024). "Variants impacting the function of the GUCY2D enzyme lead to severe retinal dystrophies, including LCA type 1 and autosomal dominant cone-rod dystrophy." (PMID 32976546, 2020). "Genetic etiologies of retinal dystrophy causing both autosomal dominant and recessive disease have been described in the literature and include RHO, RP1, BEST1, GUCY2D, RAX2, and RPE65." (PMID 31856884, 2019). "Those conditions are met, for instance, in LCA1 caused by null mutations in RetGC-E (GUCY2D) or LCA12 caused by mutations in RD3, two severe and prevalent inherited retinal dystrophies." (PMID 25058152, 2014).
retinal degeneration (7 papers, 2014 to 2025). Degeneration of the retina. "We identified a total of nine causal mutations, including six novel variants in RPE65, LCA5, USH2A, CNGB1, FAM161A, CERKL and GUCY2D as the underlying cause of inherited retinal degenerations in 13 of 26 pedigrees." (PMID 26352687, 2015). "Consistent with the phenotype observed in the cohort of patients analyzed in this study, the RPE65, LCA5, USH2A, CNGB1, FAM161A, CERKL and GUCY2D genes consisting mutations in 13 of the 26 pedigrees have been implicated in causing recessive non-syndromic retinal degeneration." (PMID 26352687, 2015). "Membrane bound guanylate cyclases are expressed in rod and cone cells of the vertebrate retina and mutations in several domains of rod outer segment guanylate cyclase 1 (ROS-GC1 encoded by the gene GUCY2D) correlate with different forms of retinal degenerations." (PMID 24616660, 2014). "Mutations in several other genes such as GUCY2D, RHO, CRX, etc., are also associated with both dominant and recessive retinal degeneration, but the situation is a little different for them." (PMID 33681214, 2021).
Blindness (5 papers, 2011 to 2025). Blindness is the condition of lacking visual perception defined as a profound reduction in visual perception. "Mutations in the GUCY2D gene coding for the dimeric human retinal membrane guanylyl cyclase (RetGC) isozyme RetGC1 cause various forms of blindness, ranging from rod dysfunction to rod and cone degeneration." (PMID 33109612, 2020). "This may indirectly indicate that the both GCAPs activate human RetGC1 in vivo; otherwise, a loss of GCAP1 function alone would have likely resulted in finding vision disorders similar to the recessive GUCY2D blindness." (PMID 33537894, 2021).
myopia (2 papers, 2025). "Additionally, GUCY2D (ENSP00000254854), which regulates cyclic GMP synthesis, has variants associated with high myopia, as demonstrated through genetic analyses." (PMID 40110040, 2025).
Atrophy (1 paper, 2024). Any weakening or degeneration, especially through lack of use. "CACD (CACD1, GUCY2D, OMIM #600179: autosomal dominant; CACD2, PRPH2, OMIM 179605: autosomal dominant) presents with a well-demarcated area of atrophy of the RPE and choriocapillaris, usually centered in the macula." (PMID 38610844, 2024).
autosomal recessive cone-rod dystrophies (1 paper, 2008). "Seven genes reported to be associated with autosomal recessive cone-rod dystrophies (crd), ABCA4, RDH5, CORD8, CORD9, RPGRIP1, CRX and GUCY2D were therefore included in the study." (PMID 18593457, 2008).
breast carcinoma (1 paper, 2024). "Based on our extensive search, it also identified several new potential genes associated with breast cancer progression, including HPCA, SLC9A2, SCNN1B, SULT4A1, and GUCY2D." (PMID 39768011, 2024).
Jalili syndrome (1 paper, 2024). Jalili syndrome is characterized by the association of amelogenesis imperfecta (AI) and cone-rod retinal dystrophy (CORD). "These include TRPM1-congenital stationary night blindness, CRB1-RP, CNM4 Jalili syndrome, retinal degeneration in Usher Syndrome (; NCT05158296; NCT04765345), and other forms of LCA including GUCY2D-LCA (LCA1) and AIPL1-LCA (LCA4)." (PMID 37443335, 2024).
retinal disorder (5 papers, 2018 to 2025). Any disease or disorder of the retina. "Several mutations spread along the entire sequence of the guanylyl cyclase Gucy2d are implicated in retinal disorders, including LCA." (PMID 38373798, 2024).
GUCY2D also shares sentences with these, for which no sentence is quoted: congenital blindness (4 papers); cone dystrophy (3); Leber congenital amaurosis 1 (3); tumor (3); Ciliopathies (2); autism (1); bone marrow diseases (1); cancer (1); choroidal dystrophy (1); genetic disorder (1); keratoconus (1); nyctalopia (1); retinal diseases (1).